INS (insulin)
Diseases named in the same sentence as INS in open-access papers (continued):
Sharing a sentence is not in itself a finding about the gene and the disease.
Insulin resistance (continued). "However, reports on associations between insulin secretion or insulin resistance and vitamin D have been inconsistent." (PMID 24868538, 2014). "Chronic elevation of IL-6 levels in obese and type II diabetics may be associated with insulin resistance, while acute transient increase can enhance insulin sensitivity." (PMID 24563869, 2014). "Furthermore, in the normal glucose-tolerant children and adolescents, K23 allele carriers had a significantly higher insulin response to oral glucose loading, suggesting a compensatory insulin secretion in the presence of insulin resistance." (PMID 25309595, 2014). "Again, we propose that glucose and insulin levels may be both measured after a sugar load test and these values may provide a better estimate of the association of insulin resistance and breast cancer risk." (PMID 24911052, 2014). "Individuals with impaired glucose tolerance also tended to have decreased liver ENPP1 protein, and the pattern of liver ENPP1 protein abundance in the IGT and T2DM groups is likely caused by high circulating levels of insulin as both groups had moderate to severe insulin resistance respectively." (PMID 25539584, 2014). "In addition to SOCS3, the lipid-dependent kinases, PKC family has been reported to inhibit several components of the insulin signaling pathway, among the 10 isoforms, PKCε is the isoform most often implicated in association with hepatic insulin resistance." (PMID 25160038, 2014). "However, the hepatic overexpression of a dominant negative form of raptor enhances AKT phosphorylation and restores insulin sensitivity in K/KAy mice with genetic obesity-associated insulin resistance." (PMID 23696823, 2013). "Nevertheless, we have a hypothesis that low IGFBP-7 levels may be related to increased insulin and consequently associated to insulin resistance." (PMID 24180466, 2013). "The logistic regression analysis showed that higher eosinophil percentage was associated with decreased risk of elevated fasting serum insulin and insulin resistance with the first tertile of eosinophil percentage as reference after adjustment for the full confounders in NGT." (PMID 23894289, 2013). "Cytokine secreting macrophages may affect the insulin signalling pathway and cause increased insulin resistance." (PMID 23467680, 2013). "Insulin resistance is the primary feature underlying type 2 diabetes (T2D) but it also exists across a continuum in the general population, and to varying extents it disrupts insulin action in cells, which can cause a wide spectrum of signs and symptoms." (PMID 23801097, 2013). "Using two common VDR polymorphism data suggests they may influence insulin secretion, insulin resistance an serum HDL-cholesterol in our highly heterogeneous population." (PMID 23855914, 2013). "This may lead to functional resistance to insulin and leptin, which may underlie permanently an increase in food intake, overweight, and insulin resistance." (PMID 24455747, 2013). "The symptom of T2DM of ob/ob mice attenuates with age, being manifested by the continuous decline of plasma insulin levels in the second year of life, with a consequent effect of glucose tolerance and insulin resistance improvement and a loss of adipose body weight." (PMID 23671868, 2013). "In subclinical hypothyroidism, diminished rate of insulin stimulated glucose transport rate caused by perturbed expression of glucose transporter type 2 gene (GLUT 2) translocation may lead to insulin resistance." (PMID 23671867, 2013). "This receptor causes suppression of insulin action and promotes insulin resistance." (PMID 23781121, 2013). "The present findings demonstrate that tectorigenin attenuated insulin resistance (IR) associated with endothelial dysfunction through inhibiting ROS-related inflammation in endothelium cells, as well as facilitating insulin IRS-1/PI3K/Akt/eNOS signaling pathway." (PMID 23840461, 2013).
Insulin resistance (continued). "Thiazolidinediones (TZD) represent a class of oral hypoglycemic agents that have been shown to improve insulin action and reverse some of the metabolic processes responsible for the development of insulin resistance and, finally, type 2 diabetes in predisposed subjects." (PMID 23935612, 2013). "Independent of ethnicity, age, and sex, obesity represents the most important risk factor for insulin resistance as well as increased circulating levels of insulin, leading to decreased insulin sensitivity and impaired β-cell function, thereby developing type 2 diabetes in youth." (PMID 24454364, 2013). "Excess triglyceride accumulation causes insulin resistance by directly interfering with hepatic insulin signaling; however, it is still unclear whether there is a causal relationship between hepatic steatosis and insulin resistance." (PMID 23451068, 2013). "At multivariate analysis insulin resistance was the only parameter associated with A wave velocity, and this could represent the functional aspect of an increased insulin resistant role in promoting impaired subclinical diastolic cardiac function." (PMID 24171177, 2013). "Furthermore, leptin interferes with insulin signaling, and plasma levels of leptin directly correlate with the degree of insulin resistance in patients with T2D, whose association with breast carcinoma has been well studied." (PMID 23819063, 2013). "Since hypothalamic inflammation has been associated with central insulin resistance, the present data are also in line with our previous work, reporting impairment of hypothalamic insulin signaling and abolition of insulin hypophagia by the soy diet while the fish diet exerted a protective effect." (PMID 24049658, 2013). "Furthermore, miR-29 is up regulated in muscle, fat and liver in type 2 diabetic rats and caused insulin resistance in adipocyte and the overexpression of miR-29 inhibits the activation of Akt which is a crucial mediator of insulin signal transduction." (PMID 24349318, 2013). "Indeed, within healthy controls, high circulating OC was associated with markers of lower insulin resistance and increased insulin sensitivity." (PMID 23691179, 2013). "If a PI is the suspected cause of insulin resistance, studies in adults and children have shown switching to a PI-sparing regimen or unboosted atazanavir could improve insulin sensitivity." (PMID 23782481, 2013). "Similarly, defects in proper insulin signaling and the signaling pathways leading to insulin resistance are directly linked to the onset of type 2 diabetes, obesity, and Alzheimer's disease." (PMID 23022959, 2013). "Chemokines and proinflammatory stimuli activate the nuclear factor-κB and JNK pathways in insulin sensitive tissues and may cause insulin resistance." (PMID 23922760, 2013). "Homozygosity for the leptin receptor (LEPR) rs3790433 G allele was also associated with increased MetS risk, which may be accounted for by increased risk of elevated insulin concentrations and insulin resistance." (PMID 23306188, 2013). "Functionally, cattle-specific miRNAs might be associated with the insulin signalling pathway, and thus potentially have a role in the evolution of insulin resistance in ruminants." (PMID 24020371, 2013). "The aim of our present study is to determine the effect of Gelam honey extract and quercetin on the stress activated NF-κB and MAPK pathways and IRS-1 serine phosphorylation causing insulin resistance and the Akt activated insulin signaling pathway, causing increase in insulin content." (PMID 24324490, 2013). "Chronic maternal consumption of an HF diet is associated with insulin resistance in the progeny due to various causes, including the fact that HF diet consumption impairs glucose uptake in the skeletal muscle, alters insulin signaling, leads to beta cell failure and promotes obesity." (PMID 23383269, 2013).
Insulin resistance (continued). "In numerous experimental models, these proinflammatory cytokines disrupt normal insulin action in fat and muscle cells, and may be a major factor in causing the whole-body insulin resistance observed in patients with visceral adiposity." (PMID 24072087, 2013). "As such, our results suggest that PPAR-γ suppression could affect energy homeostasis and insulin-induced glucose metabolism in skeletal muscle, which could then cause mitochondrial dysfunction and insulin resistance." (PMID 24098655, 2013). "Insulin resistance is the main outcome caused by nutrient overload, lipids, infections, and sepsis-induced inflammation that affects insulin-sensitive tissues, such as the liver, muscle, adipose tissue, and hypothalamus, and which also promotes defects in cell signaling pathways and homeostasis." (PMID 23840101, 2013). "This may indicate a higher risk of insulin resistance among individuals with low Prudent dietary pattern scores which had higher than normal fasting insulin concentrations." (PMID 23398686, 2013). "A higher BMI value was strongly associated with higher insulin levels and insulin resistance." (PMID 23311535, 2013). "Here we demonstrate what was also reported by others that obesity increases JNK activation in skeletal muscle that could potentially impair insulin signaling accounting for the development of obesity-associated insulin resistance in this tissue." (PMID 23349837, 2013). "On the basis that insulin decreases the production of this strong vasodilator, Parker and coworkers suggested that hypertension associated with insulin resistance and hyperinsulinemia (i.e., metabolic syndrome) would be due partly caused by the lack of proper PGI2 release." (PMID 23573411, 2013). "We need, however, a new strategy to predict the individual risk of insulin resistant patients, including those receiving chronic therapies with drugs that worsen insulin resistance, not only in terms of metabolic complications, but also in terms of cancer risk or cancer resistance to therapy." (PMID 24115945, 2013). "The peptide hormone insulin is produced by beta cells in the pancreas and released in response to hyperglycemia, which is associated with insulin resistance, aberrant glucose metabolism, chronic inflammation, and the production of other metabolic hormones, such as IGF-1, leptin, and adiponectin." (PMID 24280167, 2013). "Because the association between the COBLL1 C allele and lower insulin resistance is present early in life and thus it is likely to persist over time, it would be interesting to examine if the changes in insulin levels are also associated with a reduction of the long-term risk for type 2 diabetes." (PMID 23463496, 2013). "Previous studies have shown that LSG leads to improvement in glucose tolerance, which may be explained by the decrease in insulin resistance due to weight loss and by the increase in insulin secretion due to enhanced GLP-1 secretion." (PMID 23823622, 2013). "Usually, insulin resistance and hyperinsulinemia are the main clinical causes of type 2 diabetic among patients, and these indicate the presence of an impaired biological response to either exogenously administered or endogenously secreted insulin." (PMID 23983807, 2013). "Patients with HIV-associated lipodystrophy show both impaired insulin-stimulated whole-body oxidative glucose disposal and impaired nonoxidative glucose disposal indicating peripheral insulin resistance." (PMID 24303139, 2013). "Advanced renal damage may also in itself affect glucose metabolism and both may cause insulin resistance and impaired insulin secretion." (PMID 24868254, 2013). "By a lipid-guided exploration, a set of significant biological pathways and suspected genes were identified to be insulin resistance-associated, including one carbon pool by folate, arachidonic acid metabolism, and insulin signaling pathway, which cannot be directly found by gene expression profile." (PMID 23369247, 2013).
Insulin resistance (continued). "Similarly in the LIPGENE-SU.VI.MAX study rs7903146 was associated with increased MetS risk, arising from their impaired insulin sensitivity, greater insulin resistance, increased abdominal obesity and hypertension." (PMID 23306188, 2013). "Studying skeletal muscle in relation to insulin resistance and its associated diseases such as the metabolic syndrome is particularly important, as under normal physiological conditions this tissue is the major site of insulin-stimulated glucose disposal." (PMID 24358323, 2013). "Insulin resistance is a strong, independent risk factor for asthma development, but it is unknown whether a direct effect of insulin on the lung is involved." (PMID 24204385, 2013). "The pro-inflammatory cytokines TNFα and IL-6 have been shown to trigger phosphorylation of IRS-1, thus exerting an inhibitory action on insulin signaling; accordingly, genetic ablation either of TNFα or of its receptor can improve insulin resistance caused by obesity in rodent models." (PMID 23698776, 2013). "Thus, as calculated by HOMA model, the diabetic subjects had a marked insulin resistance and impaired insulin secretion suggesting a relative insulin deficiency." (PMID 23853613, 2013). "Insulin resistance and insulin secretion defects were two risk factors in type 2 diabetes." (PMID 24353633, 2013). "Inhibition of 11β-HSD1 by insulin may contribute to insulin sensitization through a reduction in glucocorticoid, which is a risk factor for insulin resistance." (PMID 24367624, 2013). "Since abnormal hyperinsulinemia has been found to diminish insulin sensitivity, elevated serum levels of insulin may cause insulin resistance by downregulating insulin receptors and desensitizing postreceptor pathways." (PMID 23983807, 2013). "This could well be a sign of an increased insulin secretion, associated with hypertrophy and hyperplasia of the β-cells, that accompanies the physiological insulin resistance developing during the second and third trimesters of normal pregnancies." (PMID 24319455, 2013). "Interestingly, inactivation of SphK1 augmented the effect of PA induced insulin resistance in L6 myotubes, which was associated with further inhibition of insulin stimulated PKB and GSK3β phosphorylation, glucose uptake and the accumulation of sphingosine." (PMID 24376889, 2013). "Moreover, exercise and weight loss as well as insulin sensitizers like thiazolidinediones improve insulin resistance, while exerting direct effects on oxidative capacity." (PMID 23383072, 2013). "Insulin-resistance linked ovarian hyperandrogenism could also contribute to decreased fertility, and the two patients became pregnant after initiation of insulin-sensitizers (metformin)." (PMID 23849162, 2013). "Fasting insulin and WC were almost equally associated with MetS suggesting that both insulin resistance and adiposity may be the key features of the syndrome." (PMID 23853615, 2013). "Polymorphisms at the GCKR gene region were firstly identified to be associated with triglycerides levels by genome wide association studies, and the alleles which increasing triglycerides levels were found to lower the glucose, insulin levels and insulin resistance by different association studies." (PMID 23383164, 2013). "Insulin resistance is well-documented as the hallmark of MetS, but occurs with a differential response intensity of target tissues such as adipose, liver and muscle tissues to a given insulin level." (PMID 23688034, 2013). "This suggestion is supported by the European Group for the Study of Insulin Resistance: relationship between insulin sensitivity and cardiovascular disease risk (EGIR-RISC) collaboration, which prospectively evaluates the role of insulin resistance in CVD risk." (PMID 22720085, 2012).
Insulin resistance (continued). "It is clear from these previous studies that 14-3-3 proteins play an essential role in insulin desensitization and therefore may be associated with insulin resistance induced by a chronic hyperglucose and hyperinsulin milieu." (PMID 22970290, 2012). "Although our results suggest a beneficial effect of anti-TNF treatment on insulin signaling in RA patients with high insulin resistance, the clinical importance of such treatment in reducing risk of cardiovascular disease in the long term remains to be determined." (PMID 22691241, 2012). "Interestingly, 30 genes are associated with regulation of insulin signal transduction pathways, development, and function of pancreatic islets, insulin secretion, and insulin resistance." (PMID 22655170, 2012). "Elevated IMCLs, in association with the increased production of lipid metabolites such as acyl coenzyme A (CoA), diacylglycerol (DAG), ceramides, and reactive oxygen species (ROS), can affect insulin signaling and contribute to insulin resistance associated with type 2 diabetes." (PMID 22203837, 2012). "Insulin resistance is a ubiquitous correlate of obesity and a central component of type 2 diabetes and is characterized by a decreased response to insulin, linked to perturbation of insulin signaling." (PMID 23272222, 2012). "This important finding suggests that the increased IL-6 production associated with obesity and insulin resistance may in fact represent a mechanism for increasing the production of insulin, an idea that warrant further investigation." (PMID 22761857, 2012). "When assessing the effects of diet on insulin sensitivity and IMCLs content both severity of the caloric restriction, duration of the intervention, amount of weight loss and perhaps severity of insulin resistance and duration of T2DM have to be taken into account." (PMID 22675355, 2012). "Therefore, ROS-induced loss of insulin or insulin resistance is responsible for ultimate onset of type 1 and type 2 diabetes and their vascular complications, respectively." (PMID 22611498, 2012). "The insulin resistance in turn would cause impaired glucose tolerance, however most individuals are able to adapt to the insulin resistance through a compensatory increase in insulin secretion resulting in normal circulating glucose levels." (PMID 23201760, 2012). "In this line, pregnant women with altered glucose metabolism showed similar mZAG circulating levels to NGT women, despite the inverse association with the insulin resistance parameters (insulin, HOMA-IR index and triglycerides) detected in the univariate analysis." (PMID 23272038, 2012). "Previous research demonstrated that the proinflammatory cytokine TNFα blunts the insulin signaling pathway therefore causing insulin resistance by activating the JNK1/2 signaling pathway which is involved in serine phosphorylation of IRS1 (insulin receptor substrate 1)." (PMID 22506114, 2012). "Notably, milk consumption in prepubertal boys has been shown to increase serum insulin concentrations associated with the induction of insulin resistance." (PMID 22891897, 2012). "An important next step in this line of investigation would be a larger and longer study examining the effect of HCQ on insulin sensitivity, focusing on subjects with systemic inflammatory conditions, a population at an increased risk for insulin resistance and DM." (PMID 22676348, 2012). "In case B, active mTOR is a cause of insulin resistance and low insulin signaling." (PMID 22683661, 2012). "Pregnancy is a hyperinsulinemic state which may develop into impaired glucose tolerance if insulin secretion is unable to compensate for pregnancy-associated insulin resistance." (PMID 22518122, 2012). "In the obese state, the risk would be increased due to insulin resistance, which may accompany obesity and impairment of glucose-stimulated insulin secretion attributable to UCP2 at-risk genotype." (PMID 22533685, 2012).